STAT5B (signal transducer and activator of transcription 5B)
Diseases named in the same sentence as STAT5B in open-access papers (continued):
Sharing a sentence is not in itself a finding about the gene and the disease.
lobular breast carcinoma (1 paper, 2023). "Another dataset also suggested a downregulation of STAT5B expression in invasive ductal and lobular breast carcinoma (FC = −2.067, P = 2.51E–36)." (PMID 36862902, 2023).
lupus (1 paper, 2016). "In addition, the gene expression of sh2d1a, map3k1, spn and stat5b was enhanced after NaCl treatment, consistent with the findings in lupus CD4+T cells." (PMID 27325182, 2016).
lymphoblastic lymphoma (1 paper, 2018). A lymphoma composed of immature small to medium-sized precursor lymphoid cells (lymphoblasts). "Transgenic mouse models expressing high levels of murine Stat5a or Stat5b developed lymphoblastic lymphoma at low penetrance (5%–25%) and with a late onset (up to 456 days)." (PMID 29200404, 2018).
lymphoproliferative disorders (1 paper, 2019). "This mutation is known to activate STAT5B but was previously thought to be restricted to lymphoproliferative disorders." (PMID 30573779, 2019). "Of the other variants, STAT5B N642H (NM_012448: c.A1924C) was seen in two cases (E11076 and E11493) and stood out as this is a known driver mutation in lymphoproliferative disorders." (PMID 30573779, 2019). "Other somatic STAT5B and STAT3 mutations have been identified in lymphoproliferative disorders." (PMID 30573779, 2019).
memory (1 paper, 2021). The activities involved in the mental information processing system that receives (registers), modifies, stores, and retrieves informational stimuli. "Interestingly, brain-specific Stat5a/Stat5b knockout mice exhibit memory deficits, suggesting that STAT5 is a downstream signaling pathway potentially recruited by GHR to modulate memory." (PMID 33440789, 2021).
metastatic prostate carcinoma (1 paper, 2013). A carcinoma that arises from the prostate gland and has spread to other anatomic sites. "Among these, SOX4, STAT3 and STAT5B are known regulators of metastatic prostate cancer through the regulation of genes involved in miRNA processing, transcriptional regulation, and developmental pathways." (PMID 23782521, 2013).
myeloproliferative disorder (1 paper, 2013). A clonal hematopoietic stem cell disorder, characterized by proliferation in the bone marrow of one or more of the myeloid (i.e., granulocytic, erythroid, megakaryocytic, and mast cell) lineages. "Nevertheless, upregulation of SOCS3 has been reported in CTCL and other malignancies in association with elevated JAK-STAT signalling, and in JAK2V617F positive myeloproliferative disorders together with STAT3 and STAT5B, consistent with our findings." (PMID 23372669, 2013).
myxofibrosarcoma (1 paper, 2023). A malignant fibroblastic neoplasm arising from the soft tissue. "Our findings provide not only prognostic insight into future risk stratification but also a novel biomarker-guided therapeutic approach to targeting angiogenesis in aggressive myxofibrosarcomas which harbor the vulnerable PAK1/STAT5B/CSF2 proangiogenic axis." (PMID 37564209, 2023). "Upon nuclear entry together with STAT5B, PAK1 co-transactivated the pro-angiogenic CSF2 gene, encoding granulocyte-macrophage colony stimulating factor 2 (a.k.a GM-CSF), to increase CSF2 expression, hence enhancing angiogenesis in myxofibrosarcomas." (PMID 37564209, 2023). "These clues further infer a question of whether, in a positive feedback loop, overproduced CSF2 in myxofibrosarcoma cells depends on nuclear PAK1 to invigorate the activity of JAK2/STAT5B cascade." (PMID 37564209, 2023). "Conclusively, the nuclear entry of overexpressed/activated PAK1 endows myxofibrosarcomas with pro-angiogenic function, highlighting the vulnerable PAK1/STAT5B/CSF2 regulatory axis." (PMID 37564209, 2023).
NK/T-cell lymphoma (1 paper, 2017). "However, activating mutations of STAT5B have been described in some cases of NK/T-cell lymphoma as well, generating opposing interpretations." (PMID 28977998, 2017).
pancreatic adenocarcinoma (1 paper, 2022). "Furthermore, survival analysis of these genes was conducted with the Kaplan-Meier method, and as a result, MYLK, SOCS3, STAT5B, and PLAU genes were obtained with the highest mortality rate for pancreatic adenocarcinoma (PAAD) patients." (PMID 35928368, 2022).
penile cancer (1 paper, 2024). A primary or metastatic malignant neoplasm that affects the penis. "During lymph node metastasis phase of penile cancer, the expression evolution of JAK-STAT-SOCS1 axis was characterized by the upregulation of JAK3, STAT4 and STAT5B." (PMID 38774752, 2024).
periodontitis (1 paper, 2021). An acute or chronic inflammatory process that affects the tissues that surround and support the teeth. "Of the top 10 hub TFs, six “leader” immunosuppressive TF-target DEGs with plausible literature evidence were identified as key to periodontitis pathogenesis and included the down-regulated TFs (NFKB1, FOS, and JUN), as well as up-regulated TFs (HIF1A, STAT5B, and STAT4)." (PMID 33777111, 2021). "Thus, evidence suggests STAT5B and STAT4 may mediate immunosuppression during periodontitis." (PMID 33777111, 2021).
pituitary adenoma (1 paper, 2023). "JAK2/STAT5B pathway was identified as a key biological event in ER-mediated growth of pituitary adenoma." (PMID 36605480, 2023). "The expression of STAT5B was significantly positively correlated with ESR1 expression in the pituitary adenoma." (PMID 36605480, 2023). "Our further study confirmed that fulvestrant and AZD9496 significantly blocked the mRNA and protein level of STAT5B in vitro and in vivo pituitary adenoma model." (PMID 36605480, 2023). "Further studies showed that STAT5B was significantly positively correlated with ESR1 expression in pituitary adenoma." (PMID 36605480, 2023). "Given that JAK2 gene is an important upstream regulator of STAT5B gene 18, we speculate that ER inhibitors affect the JAK2-STAT5B pathway in pituitary adenoma cells." (PMID 36605480, 2023). "In this study, we found the STAT5B is positively related to ESR1 expression in pituitary adenoma." (PMID 36605480, 2023). "Both AZD9496 and fulvestrant could significantly block JAK2/STAT5B pathway in pituitary adenoma models." (PMID 36605480, 2023). "It suggests that STAT5B may be a key player in the ESR1-reuglated growth of pituitary adenoma." (PMID 36605480, 2023).
prostate tumor (1 paper, 2024). "Module 3 includes NTRK2, DDR2, and STAT5B, which have been associated with prostate tumor metastasis, and JAZF1, ZEB1, and BCL2, which have been linked to cancer progression and resistance to chemotherapy." (PMID 39347576, 2024).
ptosis (1 paper, 2017). The drooping of the upper eyelid. "We detected a novel possibly causative STAT5B mutation in a sibling pair with motor neuropathy, ptosis, short stature, and dysmorphic facial features." (PMID 28251916, 2017).
pulmonary alveolar proteinosis (1 paper, 2022). A rare lung disorder characterized by the filling of the pulmonary alveoli with proteinaceous material which stains positive with periodic acid-Schiff stain. "These deleterious loss-of-function STAT5B mutations also lead to the disruption of GM-CSF signaling, which is associated with pulmonary alveolar proteinosis (PAP)." (PMID 36755813, 2022). "Impairment in this signaling pathway can lead to the inability to initiate this protein clearance causing pulmonary alveolar proteinosis (PAP), a known complication in STAT5b deficient patients." (PMID 36755813, 2022).
rectal tumors (1 paper, 2025). "For example, STAT5B mutations were found to be significantly more prevalent in colon versus rectal tumors, an anatomical preference that may reflect divergent etiologies or tissue-specific gene regulation." (PMID 40723258, 2025).
rheumatoid arthritis (1 paper, 2012). A chronic, systemic autoimmune disorder characterized by inflammation in the synovial membranes and articular surfaces. "For example, Naf1 is highly involved in NF-κB pathway activation in rheumatoid arthritis, while Stat5b activation occurs during proliferation/oxidation-associated production of advanced glycation end products." (PMID 22558133, 2012).
Salmonella Infections (1 paper, 2022). Infections with bacteria of the genus SALMONELLA. "Combined with the cytokine receptor phosphorylation data discusses previously (IL2R and IL6R), it is reasonable to assume that STAT5B phosphorylation found here is involved in maintaining the cecal function during the initial Salmonella infection stage." (PMID 35846741, 2022).
Short stature (1 paper, 2015). A height below that which is expected according to age and gender norms. "Monogenic causes of short stature which are associated with a low serum IGF-I level and normal or high GH levels could comprise the defects of GH1 (bioinactive GH), GHSR (ghrelin receptor), GHR (GH receptor), STAT5B, IGF1, and IGFALS." (PMID 26777041, 2015).
Splenomegaly (1 paper, 2022). Abnormal increased size of the spleen. "Due to stochastic activity of the Foxp3 promoter, constitutive overexpression of STAT5B-CA led to progressive splenomegaly and hematopoietic neoplasia in Foxp3YFP-Cre/YRosa26Stat5b-CA/wt mice (data not shown), similar to that after STAT5 activation in other hematopoietic compartments." (PMID 35874700, 2022).
vitamin D deficiency (1 paper, 2024). A nutritional condition produced by a deficiency of VITAMIN D in the diet, insufficient production of vitamin D in the skin, inadequate absorption of vitamin D from the diet, or abnormal conversion of vitamin D to its bioactive metabolites. "Expression of the Chr17q21.2 genes Stat3, Stat5a, and Stat5b was not affected by vitamin D deficiency." (PMID 38567749, 2024).
tumor (111 papers, 2007 to 2025). "Previous studies have reported that various tumor-associated genes are regulated by STAT5A/STAT5B, which maintain multiple cancer-related pathways." (PMID 41048344, 2025). "The frequent downregulation of STAT5B in multiple cancers suggests a tumor-suppressive function, while the consistent association of higher STAT5B expression with improved survival highlights its potential clinical relevance." (PMID 41301421, 2025). "These structural distinctions likely underpin the divergent biological behaviors observed: STAT5B exhibits predominantly tumor-suppressive associations across epithelial cancers, while STAT5A demonstrates dual or even opposing effects in certain malignancies." (PMID 41301421, 2025). "Two adjacent genes encoded STAT5 in mammals, namely, Stat5a and Stat5b, which drive tumor development, metastasis, survival and drug resistance to treatment, NK cell development, maturation, survival, and cytotoxicity." (PMID 36324680, 2022). "In summary, we demonstrate the activation of STAT3 and STAT5B in feline alimentary tumour cells, and identify the activating mutation STAT5BN642H in feline EATL type II, as frequently observed in human MEITL patients." (PMID 34680385, 2021). "Here, the established role of STAT5B as cell cycle regulator comes into play; STAT5B controls cell cycle progression and its loss interferes with proliferation and motility of tumor cells." (PMID 30679796, 2019). "Recurrent somatic point mutations in STAT5B in mature NK/T cell neoplasms recently concentrated research on STAT5B mutations and how they drive disease." (PMID 31690038, 2019). "In contrast to our expectations that an impaired NK cell-mediated tumor surveillance accelerates leukemogenesis, STAT5B-deficient animals disease significantly later." (PMID 30679796, 2019). "As we know, STAT5b is a vital regulator in the proliferation, differentiation and survival of tumor cell and other aggressive lymphoid maligancies harboured STAT5b mutations." (PMID 28427176, 2017). "Further, we analyzed STAT5B mutation status in primary tumor samples." (PMID 40723258, 2025). "Second, the molecular mechanisms underlying STAT5B’s tumor-suppressive effects remain to be fully defined, particularly whether they involve canonical transcriptional programs, non-canonical chromatin regulation, or both." (PMID 41301421, 2025). "A recent continuous cohort study found that STAT5B may serve as a tumor-associated molecular determinant of neurocognitive deficits in patients with diffuse glioma." (PMID 38883967, 2024). "Particularly STAT3 and STAT5B are constitutively activated either by gain-of-function mutations in JAKs or other upstream oncogenes or less frequently by activating mutations and have been linked to tumour initiation and progression." (PMID 34680385, 2021). "In parallel, direct comparative analyses of STAT5A and STAT5B within the same tumor types are needed to disentangle their overlapping and divergent functions, ultimately enabling the development of isoform-specific diagnostic tools and therapeutic strategies." (PMID 41301421, 2025). "This meta-analysis reveals a complex landscape in which STAT5B functions largely as a tumor suppressor but retains oncogenic potential in specific contexts." (PMID 41301421, 2025). "Conversely, compared to PD doublets, both CR and PR activated STAT5A and/or STAT5B which can have dual roles as tumour promoting or tumour suppressing TFs48." (PMID 40280979, 2025). "While STAT5A has been characterized as a context-dependent modulator of tumor progression, the prognostic significance of STAT5B remains less clear." (PMID 41301421, 2025). "To explore the role of STAT5B in cancer, we compared its mRNA expression levels in tumor versus normal tissues using the GEPIA2 database." (PMID 41301421, 2025). "The highly homologous transcription factors STAT5a and STAT5b are overactivated in many human tumor types." (PMID 41320753, 2025).
tumor (continued). "Accordingly, comparative analyses of STAT5A and STAT5B in matched tumor contexts are needed to delineate their overlapping yet functionally distinct roles in cancer biology." (PMID 41301421, 2025). "The present study provides systematic evidence that STAT5B plays an important role in cancer biology, with distinct patterns of expression and prognostic impact across tumor types." (PMID 41301421, 2025). "This uniform absence of overexpression, together with the widespread downregulation, underscores STAT5B’s potential role as a broadly conserved tumor-suppressive factor, in contrast to many oncogenes that show tissue-restricted overexpression patterns." (PMID 41301421, 2025). "Using RT-PCR, the expression levels of PIP, PIAS3, SOCS3, STAT5A, and STAT5B were verified at the level of mRNA isolated from the tumor’s margin (normal) (n = 40), mastopathy (n = 16), and BC tumor tissue (n = 42)." (PMID 40003884, 2025). "To situate these findings, we compiled a literature-based summary of cancer-specific roles of STAT5B (oncogenic vs. tumor-suppressive) alongside our meta-analytic results." (PMID 41301421, 2025). "PAX5 has been shown to act as a tumor suppressor in the B-lymphoid lineage and haploinsufficiently synergize with Stat5b-CA to induce ALL in mice." (PMID 39469218, 2024). "In vivo, experiments showed that STAT5B knockdown inhibited tumor growth by suppressing the expression of ARRB2 and phosphorylation of ERK1/2." (PMID 38341429, 2024). "Activation of STAT1, STAT2, STAT3, STAT4, and STAT6 was observed in expanded bile duct epithelium and tumor cells, while expression of STAT5a and STAT5b was found in macrophages and connective tissues surrounding the tumor." (PMID 39290697, 2024). "Through transcription factor analysis, we can see that State7, 6, 5, 3, representing tumours, is enriched in STAT5B, TFAP2C, KLF1, ZBTB7A, etc.." (PMID 38613345, 2024). "While STAT3 has been extensively studied in solid tumors, including GBM, less is known about the role of STAT5A and STAT5B in tumor progression." (PMID 38892466, 2024). "Taken together, it was implied that up-regulation of STAT2, STAT4, and STAT5B meant down-regulation of HNSC tumor stemness characteristics." (PMID 36968603, 2023). "On the whole, it was illustrated that higher the expression of STAT1, STAT2, STAT3, STAT4, STAT5A, and STAT5B, the lower the tumor purity." (PMID 36968603, 2023). "As a result, the level of STAT5A and STAT5B were significantly downregulated in tumor tissues compared with normal tissues (P < .05)." (PMID 36862902, 2023). "Dual inhibition of the transcription factors STAT5a and STAT5b is a valuable approach with promising applications in tumor biology." (PMID 36300584, 2023). "STAT5, particularly, the STAT5B isoform, promotes mouse mast cell proliferation and survival, neoplasia, and IgE-mediated degranulation and cytokine secretion release." (PMID 36230993, 2022). "Moreover, HIF-1α/STAT5B signaling could also be directly linked to tumor epileptogenicity." (PMID 36295510, 2022). "The expression of STAT5B was positively associated with GBMLGG, LGG, and PCPG, while STAT5B expression was negatively related to all other tumor types." (PMID 36176415, 2022). "Even upon transfer into lymphocyte-replete PyMT hosts, these STAT5B-CA expressing αβILTCK progenitors colonised tumour tissue, expanded, differentiated into αβILTCK effector cells, and diminished tumour growth." (PMID 35768418, 2022). "Activated STAT5B is involved in maintaining ovarian CSCs; chemotherapy resistance and tumor immune response are closely related." (PMID 36524006, 2022). "Our analysis suggests that increased DVL-1 expression correlates with decreased expression levels of several immune cell genes and anti-tumor immune cell signaling regulators such as STAT5B." (PMID 34659647, 2021).